IL6 (interleukin 6)
Diseases named in the same sentence as IL6 in open-access papers (continued):
Sharing a sentence is not in itself a finding about the gene and the disease.
cancer (continued). "Hypoxia-induced Nox4 and NADPH were shown to increase IL-6 and IL-8 levels in RCC, thereby increasing the invasion of cancer cells, indicating a positive feedback loop between IL-6/8 and YAP/TAZ during the progression of RCC." (PMID 37190141, 2023). "SOCS1/3 are negative regulators of the IL-6/STAT3/NFKB axis, whose dysfunction leads to various cancers." (PMID 38023123, 2023). "It total, 32 genes, which included IL6 and SP1 of the top 10 high-priority genes, were common for pathways in cancer (hsa05200) and pathways of neurodegeneration (hsa05022)." (PMID 37298337, 2023). "Generally, CAFs promote the malignant progression of cancer cells by secreting cytokines, chemokines, and proangiogenic factors, including CXCL12, TGF-β1, VEGF, PDCF, IL-6 and CXCL16." (PMID 38057830, 2023). "Enhanced host immune responses (a significant increase in IL-2, IL-6, IFN-γ,CD56+ cells and NK activity compared with baseline) in patients with advanced-stage cancer." (PMID 36969071, 2023). "Here, it was observed that the expression of IL-6, IL-10, IL-1β and VEGF were found to be significantly upregulated in supernatant from MDSC in comparison to cancer cell supernatant." (PMID 38304256, 2023). "As demonstrated by Briukhovetska D, IL-6 is capable of inducing angiogenesis through the activation of NF-κB, leading to the secretion of VEGF by cancer cells, promoting cell proliferation, invasion, and inhibiting apoptosis." (PMID 36873124, 2023). "Adipocytes secrete many adipokines, cytokines, and chemokines (i.e., IL-1b, TNF-α, IL-6, TGF-β) that affect inflammation and fibrosis which promote cancer development." (PMID 37491420, 2023). "Although IL-6 is the primary cytokine in the interplay between SARS-CoV-2 and cancer, there are others involved as well currently under investigation." (PMID 37055774, 2023). "In monocytes and macrophages, cancer EVs can activate Toll-like receptor-mediated signaling cascade, triggering NFκB- and STAT3-mediated production of proinflammatory cytokines – IL-6, IL-8, IL-1β, CCL2, G-CSF, and TNF-α." (PMID 37397375, 2023). "We found that MDSC secreted cytokines IL-6, IL-10, IL-1β are the dominant factors elevating MDR expression in cancer cells, neutralization of MDSC secreted IL-6, IL-10, IL-1β reversed the MDR trait." (PMID 38304256, 2023). "We found that some cancer-related pathways were significantly activated in the high IAS group, for example, ANGIOGENESIS, IL2_STAT5_SIGNALING, IL6_JAK_ STAT3_SIGNALING." (PMID 38025711, 2023). "IL-6 is secreted by various cell types in TME, including immune cells, stromal cells, and cancer cells, inducing the activation of Janus kinase (JAK)/STAT3 signaling, which in turn drives immunosuppression." (PMID 38313431, 2023). "Our study found that plasma IL-6 and IFN-γ levels were significantly higher within the Cancer TIF1-γ-DM group than in the Non-cancer TIF1-γ-DM and HC groups." (PMID 36357631, 2023). "Few articles investigated the predictive value of inflammatory biomarkers [interleukin (IL)-1β, IL-6, IL-10, TNF-α, and MMP-2 and -9] in the peritoneal fluid of cancer patients who underwent surgery and experienced AL in different locations." (PMID 37601530, 2023). "IL-6 and TNF-α induce the proliferation of oval cells, which are putative cancer progenitor cells that appear in severe liver injury." (PMID 37896221, 2023). "Astrocytes then secrete IL-6, TNF-α, IL-1β, IL-23, and other signalling molecules that promote cancer cell proliferation." (PMID 37056723, 2023). "PTX3 is expressed and released by different cell types at the site of inflammation, e.g., innate immune cells, stromal cells, as well as cancer cells, in contrast with CRP or SAP, which are primarily produced within the liver due to IL-6 mediated inflammation." (PMID 38136377, 2023).
cancer (continued). "MDSCs influence CSC biology through three IL-6-dependent phosphorylation of STAT3 and nitric oxide (NO)-mediated NOTCH signaling pathways which maintain continuous and potent IL-6/STAT3 activation and impact cancer stemness." (PMID 38090567, 2023). "Some pathways showed dual roles such as Kras signaling, interferon gram and alpha response, IL6/JAK/STAT3, IL2/STAT5 signaling were negatively enriched in HOXC10 for CESC, COAD, ESCA, HNSC but were positively enriched in HOXC10 for other cancers." (PMID 38154103, 2023). "P35 was a vital cancer suppressor gene, and IL-6, secreted by CAF, has been reported to exert a protective effect on cancer cells." (PMID 37784082, 2023). "Therefore, we postulate that the inhibitory effects of SC-1 might provide an intervention point to arrest the vicious circle of the autocrine feed-forward loops between IL-6 and TGFβ during tumorigenesis and to stimulate possible strategies for cancer treatment." (PMID 37511415, 2023). "We find that inhibiting IL-6 and/or granulocyte colony stimulating factor (G-CSF)-mediated MEK signaling cascade prevents chemotherapy-induced cancer dormancy escape." (PMID 37699010, 2023). "IL-6/JAK1/STAT3 signaling has been recognized as a key mechanism for cancer drug resistance and cancer stemness." (PMID 37440925, 2023). "No change in IL-6 is important because in cases where there is the hyperactivation of this interleukin, the IL-6/JAK/STAT3 pathway is also hyperactivated, which occurs in many types of cancer." (PMID 36985286, 2023). "If CRP, IL‐6 and YKL‐40 were combined, the AUC was 0.71 for predicting cancer in the cohort of patients with non‐specific signs and symptoms of cancer." (PMID 36440611, 2023). "Activation of HIF‐1α triggers the transcription of genes involved in cancer and immunity, including cytokines IL8, IL6, ANGPTL4, VEGF and PDGF, which are commonly observed in SASP." (PMID 36660875, 2023). "SATII RNA in sEVs induces the senescence of surrounding normal and cancer cells and promotes the secretion of tumorigenic SASP proteins such as IL-6." (PMID 38003589, 2023). "In patients diagnosed with cancer within 3 months, CRP correlated with IL‐6 (r = 0.75) and YKL‐40 (r = 0.42) and IL‐6 correlated with YKL‐40 (r = 0.46)." (PMID 36440611, 2023). "In epithelial and mesenchymal cells, during ischemia-hypoxia, inflammation and cancer, its expression is up-regulated, and relevant agents are growth factors (VEGF-C and TGF-β1), cytokines (TNF-α, IFN-γ, IL-1 and IL6), fibronectin and lipopolysaccharides." (PMID 36829453, 2023). "The present study identified VEGF-A, TNF-α, CCL2, IL-6, and IFN-γ as significant potential biomarkers indicating the presence of cancer and demonstrated a more detailed cytokine profile during diagnosis." (PMID 36357631, 2023). "Accordingly, ISG20 upregulation was associated with coagulation, epithelial-mesenchymal transition, angiogenesis, complement, and cancer/immune-related signaling, such as KRAS, PI3K-AKT-mTOR, and IL6-JAK-STAT3." (PMID 37380984, 2023). "In conclusion, our study showed that plasma CRP, IL‐6 and YKL‐40 alone or combined cannot be used to identify patients with cancer." (PMID 36440611, 2023). "IL-6 emerges as a key cytokine in the multiplication and immune evasion of both SARS-CoV-2 and cancer cells." (PMID 37759738, 2023). "To address the role of IL-6 in the responses of cancer cells to NK-LAAO treatment, we silenced IL-6 expression in A549 cells." (PMID 37385076, 2023). "Recent studies have shown that interleukin 6 (IL-6) and the major downstream effector signal transducer and activator of transcription 3 (STAT3) are pro-tumorigenic agents in a variety of human cancers, including PDAC." (PMID 36495330, 2023). "Other circulating biomarkers of inflammation, like IL‐6 and YKL‐40, are secreted by inflammatory cells, stromal cells and cancer cells." (PMID 36440611, 2023).
cancer (continued). "Emerging evidence suggests that Schwann cells promote cancer cell metastasis by secreting C-X-C Motif Chemokine Ligand 5 (CXCL5), Interleukin 6 (IL-6), and Transforming Growth Factor Beta 1 (TGF-β), or by direct cancer cell contact." (PMID 37524695, 2023). "This activation is triggered by signalling molecules released by cancer cells or immune cells, including TGFβ, RTK ligands, IL1β, and IL6." (PMID 38201468, 2023). "These included multiple ligands with previously supported roles in cancer cell invasion, including TGF-β1, IL-6, CXCL12, and MMP9, underscoring the robustness of our approach." (PMID 36881486, 2023). "For example, in prostate cancer, coculturing cancer cells with fibroblasts has been shown to maintain prostate-specific antigen production, stimulated by factors such as EGF, IGF1, and IL-6 released by CAFs following androgen deprivation therapy." (PMID 37509283, 2023). "STAT signalling is mainly regulated by interleukin-6 (IL-6) and its family members, although new pathways regulating STAT3 in cancer were recently identified." (PMID 37298475, 2023). "Remarkably, the expression of iMSC signature genes such as IL6 and CXCL3 decreased after a full elimination of the cancer cells." (PMID 37958322, 2023). "In T2-T3 stage CRC, CD90+ CAFs are the main source of IL-6 in the tumor microenvironment and can promote the expression of stem cell markers ALDH and Lgr5 in cancer cells, thereby promoting cancer development." (PMID 37124519, 2023). "TRIM28 was first identified as a STAT-binding partner and frequent crosstalk between IL-6/STAT3 and NF-κB has been observed in cancer progression." (PMID 37443302, 2023). "The combination of ROS, reactive nitrogen species (RNS), IL-6, and JAK induces DNA damage leading to genetic instability through the STAT-3 pathway, promoting cancer cell proliferation and angiogenesis." (PMID 37749514, 2023). "We determined the effect of these compounds on the secretion of IL-6 in monocultures of MCF-7 cells, to establish the effect on cancer cells in monocultures of immune cells THP-1 and in co-cultures of MCF-7 and THP-1 (1:5 proportion)." (PMID 36768935, 2023). "They showed that CIN induces cGAS-STING which subsequently increases IL-6 expression and activates STAT3 signaling, thereby promoting cancer cell survival and growth." (PMID 36717545, 2023). "A key role for IL-6/JAK/STAT3 in the regulation of the growth, survival, invasiveness, metastasis, and progression of many cancers was shown." (PMID 37753372, 2023). "Signaling molecules like IL-6 and growth factors such as TGF-β, released by nearby cancer cells or immune cells, stimulate the development of CAFs by activating the NF-κB and JAK-STAT pathways." (PMID 37784157, 2023). "M1 macrophages produce ROS, nitric oxide (NO), and pro-inflammatory cytokines, such as interleukin-6 (IL-6), IL-12, and tumor necrosis factor-α (TNF-α), which participate in the inflammatory response and suppress cancer." (PMID 37241759, 2023). "In conclusion, our study showed that IL-6 can be considered a useful biomarker for HCC stages, as well as a possible target for future therapies showing a direct role in cancer development." (PMID 37173873, 2023). "Compared to drug-sensitive cancer cells, MDR cancer cells have augmented autocrine formation of growth factors such as interleukin (IL)-1, IL-6, IL-4, and IL-8." (PMID 37062547, 2023). "Serum IL-6 and C-reactive protein (CRP) (cancer-promoting) are also elevated in SSc and correlate with clinical disease activity." (PMID 37681925, 2023). "The IL-6/STAT3 pathway is abnormally activated in HCC, which results in increased progression, invasion, and migration of the cancer cells." (PMID 37095578, 2023). "A report revealed that myofibroblast-derived IL-6 and IL-8 activate the NOTCH/HES1 and STAT3 pathways to enhance cancer stemness in colon cancer." (PMID 37046588, 2023).
cancer (continued). "Our own studies confirm the influence of cytokines (i.e., concentrations of IL-1A, IL-1B, IL-2, IL-6, IL-10, TNF, and IL-4) on the emergence of fatigue in all its dimensions in patients with cancers of the reproductive organs at various stages of treatment." (PMID 36834426, 2023). "IL6 in turns activates STAT3 signaling pathway in CRC cells and increases the cancer cell invasiveness." (PMID 37062842, 2023). "The GSEA analysis results of BIRC3 observed that various cancer-promoting pathways were enriched in the high expression group including IL2 STAT5 signaling, IL6-JAK-STAT3 signaling, KRAS signaling, PI3K-AKT-MTOR signaling and TNFA signaling via NFKB." (PMID 38130918, 2023). "In colorectal cancer, downregulation of miR-34 which targets NOTCH1 and JAG1 involved in cancer stem cell acquisition resulted in increased IL-6 signaling, which led to EMT and cancer metastasis." (PMID 37460910, 2023). "Various cytokines such as IL-6 and TNF can increase catabolism and reduce albumin synthesis in cancer patients." (PMID 37143476, 2023). "Significantly higher levels of plasma VEGF-A, TNF-α, CCL2, IL-6, and IFN-γ were observed among Cancer TIF1-γ-DM patients, especially among untreated Cancer TIF1-γ-DM patients." (PMID 36357631, 2023). "The blocking of IL-6 in the interaction of HIF-1α-expressed HCC cells and NK cells enhanced the NK cytotoxicity to cancer cells and the expression of activating receptors on NK cells." (PMID 37501379, 2023). "Elevated systemic levels of IL-6, IL-1, and TNF-α in cancer patients seem to correlate with the progression of tumors." (PMID 37755304, 2023). "HBV infection promoted the production of cytokines such as INF-γ and IL-6 by activating Kupffer cells, CTLs, and monocytes, while INF-γ inhibited the formation of neovascularization in cancer metastases." (PMID 36910607, 2023). "The ability of plasma VEGF-A, TNF-α, CCL2, IL-6, and IFN-γ levels to distinguish the presence of cancer was evaluated through the area under the curve (AUC) analysis." (PMID 36357631, 2023). "We also observed the value of serum inflammatory markers were higher in patients with anti-cancer treatments within 2 weeks, including NLR (P=0.025), PLR (P=0.048) and IL-6 (P=0.023)." (PMID 37675234, 2023). "This corroborates our observation of an increased incidence of spontaneous precancerous lesions in the colon and reproductive organs of only female CB2−/− mice and suggests a role for IL-6 and MDSCs in CB2-related cancer development." (PMID 36835468, 2023). "CRP is subject to regulation by key molecular triggers of cachexia, such as IL-6, IL-1β, and TNF-α, which not only promote cancer cell growth and safeguard cancer cells against apoptosis but also stimulate angiogenesis and metastasis." (PMID 37755304, 2023). "When the inflammasomes are abnormally activated, a variety of inflammatory cytokines and chemokines, including TNF-α, IL-1β, IL-6, IL-18, CCL2/MCP-1, are excessively secreted, which affect the development of cancer." (PMID 37020871, 2023). "We investigated and observed a positive correlation between VEGF-A and CCL2 levels, VEGF-A and IL-6 levels, VEGF-A and IFN-γ levels, and IL-6 and IFN-γ levels within the Cancer TIF1-γ-DM group." (PMID 36357631, 2023). "IL-6 signaling and its downstream player STAT3 are strongly involved in the crosstalk between cancer and stroma cells." (PMID 36639824, 2023). "Interleukin 6 is an activator of STAT3, which regulates the course of several cancers, including colorectal cancer." (PMID 37958980, 2023). "Cancer cells release signaling molecules, including TNF-α and IL-6 that reprogram lipid metabolic pathways in CAAs surrounding tumors and in distal locations to trigger local and systemic lipolysis, causing adipose atrophy and cachexia in cancer patients." (PMID 37181035, 2023).
cancer (continued). "NF-κB pathways enhance cancer cell migration and invasion by upregulating multi-drug resistance genes, pro-angiogenic factors and pro-inflammatory cytokines such as VEGFA, EGF, IL-6 and IL-8." (PMID 37190141, 2023). "Therefore, higher IL-6 levels may serve as biomarkers to distinguish advanced cancers." (PMID 36900322, 2023). "High baseline IL-6 levels in serum and tissue and increase of serum IL-6 levels early on-treatment have been correlated to poor response and survival in ICI-treated cancer patients in several studies." (PMID 37173424, 2023). "IL-6 is a pleiotropic cytokine which has heterogeneous effects in GBM, promoting cancer cell survival, metastasis, and invasion." (PMID 36839682, 2023). "Their investigative focus encompassed a suite of biomarkers—activin A, growth differentiation factor 15 (GDF-15), IL-6, interleukin-1 beta (IL-1β), and tumor necrosis factor alpha (TNF-α)—which provided a comprehensive view of cancer cachexia’s unfolding." (PMID 37755304, 2023). "While our understanding of the pro-inflammatory cytokines, IL-6 and TNF-α leading to cancer cachexia has been established, the immunopathogenesis of muscle wasting has been overlooked." (PMID 37701438, 2023). "Of particular concern is that CCL2, IL-6, and IFN-γ were still significantly increased after Bonferroni correction in the Cancer TIF1-γ-DM group." (PMID 36357631, 2023). "IL-6, an inflammatory tumor cytokine, activates a series of downstream factors by activating the IL-6/STAT3 signaling pathway, which plays a significant role in the growth and development of many human cancers." (PMID 36769245, 2023). "Plasma CCL2, IL-6, and IFN-γ levels were significantly higher in the Treated Cancer TIF1-γ-DM group than in the Non-cancer TIF1-γ-DM group." (PMID 36357631, 2023). "Inhibition of intercellular signaling between cancer cells and CAFs using Netrin-1-mAb suppresses the expression of CAF-borne cytokines such as IL-6." (PMID 37065872, 2023). "At the molecular level, RT-qPCR was used to assess gene expression of CASP8, TNF-α, and IL-6 genes in Caco-2 and COLO-205 cancer cells." (PMID 36770882, 2023). "We found that IFNA1 and IFNL1 gene transcripts resulted negligibly expressed across the pan-cancer dataset when compared to other immunosuppressive and pro-inflammatory cytokines such as TGFB1/2, PTGES2, IL1A, IL1B, IL6 and CSF1." (PMID 38239354, 2023). "The four murine cancer cells were infected with MyxV_0100 and expression of the cytokines IFN-γ, GM-CSF, IL-6, IFN-β, and the immune checkpoint-related genes FLT3L, OX40L, PD-L1, and CD47 were found elevated." (PMID 37835397, 2023). "Regarding other types of cancer, the best-characterized cytokines that mediate MSCs homing to tumors include CXCL12, IFN-γ, IL-6, IL-8 and TNF, as well as growth factors such as TGF-β, HGF, PDGF and VEGF." (PMID 37563650, 2023). "It has been previously proven that TNF-α, IL-6, and IFN-γ play decisive roles in the response of immune cells against cancer cells." (PMID 37226233, 2023). "The control group presented higher expression levels of SCFA and FFAR2, while the cancer group had higher levels of TNFAIP8, IL6, and STAT3." (PMID 37893122, 2023). "The proliferative activities of cancer cells are activated by the NF-κB signaling pathway and its downstream components, STAT 3 and IL-6." (PMID 37570775, 2023). "The blockade of VEGF-A and IL-6 signaling by Avastin, Fc-VFD, and Actemra inhibits cancer-induced angiogenesis of endothelial cells." (PMID 35895109, 2023). "TAMs produce growth-inducing hepatocyte growth factor, epidermal growth factor, TGF-β, and inflammatory IL-1β, IL-6, and TNF-α that can induce EMT in cancer cells." (PMID 36831498, 2023). "For the patients diagnosed with cancer during the remaining follow‐up period, 34% had elevated CRP, 62% had elevated IL‐6 and 37% had elevated YKL‐40." (PMID 36440611, 2023).